FOXO4 (forkhead box O4)
Diseases named in the same sentence as FOXO4 in open-access papers (continued):
Sharing a sentence is not in itself a finding about the gene and the disease.
Hyperglycemia (1 paper, 2011). An increased concentration of glucose in the blood. "The effect of hyperglycemia on Foxo4 acetylation was also tested." (PMID 21858169, 2011).
Listeria infection (1 paper, 2022). "Correspondingly, conditional deletion of FoxO4 in CD4+ T cells enhanced T cell–specific responses to Listeria monocytogenes infection in vivo." (PMID 36106640, 2022). "Furthermore, DKK3 treatment in the Listeria infection model increased bacteria burdens in the livers and spleens of FoxO4-cKO mice." (PMID 36106640, 2022). "Next, in order to validate the function of the FoxO4/DKK3 axis in vivo, we treated WT and FoxO4-cKO mice with DKK3 and the Wnt inhibitor Wnt-C59, respectively, in the Listeria infection model." (PMID 36106640, 2022).
liver diseases (1 paper, 2021). "Moreover, previous studies have emphasized FOXO4 as a contributory factor in a wide array of diverse liver diseases including that of alcohol‐induced liver disease, whereby it plays a role in hepatic inflammation." (PMID 34061461, 2021).
lung diseases (1 paper, 2020). "FOXO4 is known to decrease the activity of hypoxia-inducible factor, which is a validated biomarker for lung diseases." (PMID 32721949, 2020).
mesothelioma (1 paper, 2022). A usually malignant and aggressive neoplasm of the mesothelium which is often associated with exposure to asbestos. "In addition, the FOXO4 was a significantly protective factor in DSS, OS, and PFS for thymoma (THYM), mesothelioma (MESO), LGG, and KIRC, as well as a high risk factor in disease-free survival (DFS), DSS, OS, and PFS for pheochromocytoma and paraganglioma (PCPG)." (PMID 36555288, 2022).
muscle atrophy (1 paper, 2020). The loss of muscle tissue due to inactivity or disease. "Indeed, while FoxO4 may be able to bind MuRF1 promoter, only few atrogenes can be controlled by FoxO4 like MAFbx/Atrogin-1 in a TNF-induced muscle atrophy model or Gadd45 in denervated and fasted animals." (PMID 32933049, 2020).
neuroblastoma (1 paper, 2021). Neuroblastoma (NB) is the most common solid, extracranial childhood tumor. "Immunohistochemical analysis of human neuroblastoma SH-SY5Y cells revealed that endogenous FBXO7 and FOXO4 colocalized in cells." (PMID 34800438, 2021). "In addition, the interaction between endogenous FBXO7 and endogenous FOXO4 was confirmed in HEK293 cells, mouse neuroblastoma MN9D cells, and whole mouse brain lysates." (PMID 34800438, 2021).
oral cancer (1 paper, 2021). "In the present study, Western blotting was used to confirm the expression of FOXO4 in oral cancer cell lines CaL27 and SCC9." (PMID 34055579, 2021). "To further assess the role and relationship between FOXO4 and Prx1 in oral cancer, we detected FOXO4 protein expression in 4NQO induced tongue carcinogenesis model in Prx1+/+and Prx1+/− mice." (PMID 34055579, 2021).
pulmonary fibrosis (1 paper, 2025). Chronic progressive interstitial lung disorder characterized by the replacement of the lung tissue by connective tissue, leading to progressive dyspnea, respiratory failure, or right heart failure. "In summary, targeting the SIRT6-PPARα-mediated lipolysis and the TGF-β/SIRT7/FOXO4-regulated glutamine metabolic pathway may be a potential strategy for the treatment of pulmonary fibrosis and related diseases." (PMID 40241794, 2025).
renal fibrosis (1 paper, 2022). A final common manifestation of a wide variety of chronic kidney diseases characterized by glomerulosclerosis and tubulointerstitial fibrosis. "Firstly, the results of both ChIP assay and luciferase activity assay showed that β‐catenin promoted the binding of the OPN promoter sequence with Foxo4, another important transcription factor for renal fibrosis." (PMID 35312232, 2022).
retinal detachment (1 paper, 2013). An eye emergency condition which may lead to blindness if left untreated. "We demonstrate that Resveratrol increases the expression of FoxO1A, FoxO3A, and FoxO4 in retinal detachment." (PMID 24040416, 2013).
squamous cell carcinoma (1 paper, 2021). A carcinoma arising from squamous epithelial cells. "By employing a 4NQO-induced oral carcinogenesis mouse model, we confirmed that FOXO4 expression was reduced in 4NQO-induced squamous cell carcinoma (SCC) tongue tissues compared with those in normal tissues." (PMID 34055579, 2021).
Stroke (1 paper, 2025). Sudden impairment of blood flow to a part of the brain due to occlusion or rupture of an artery to the brain. "While our preliminary study demonstrates a possible association between FOXO4 and stroke, we believe it is too early to conclude that FOXO4 has diagnostic value for stroke." (PMID 40900757, 2025). "FOXO4 protein had a significantly high and moderate discriminatory ability in stroke patients." (PMID 40900757, 2025). "Pulse, systolic and diastolic blood pressure, respiratory rate, white blood cell, and FOXO4 protein levels were found to be significantly higher in stroke patients compared to the control group (p = 0.038, <0.001, <0.001, <0.001, <0.001 and 0.004, respectively)." (PMID 40900757, 2025). "In addition, the FOXO4 protein had a moderate discriminatory ability in predicting stroke, and its sensitivity was over 70%." (PMID 40900757, 2025). "The study’s findings suggest that FOXO4 protein could potentially serve as a valuable biomarker in the diagnosis of stroke in acute ischemic stroke patients." (PMID 40900757, 2025).
triple-negative breast carcinoma (1 paper, 2022). An invasive breast carcinoma which is negative for expression of estrogen receptor (ER), progesterone receptor (PR), and human epidermal growth factor receptor 2 (HER2). "Analysis of the mRNA expression of the FoxO family and SIRT1 in TCGA (The Cancer Genome Atlas) revealed that all genes were downregulation in tumors compared to normal tissues in TNBC (triple-negative breast cancer) (p < 0.05 for FoxO1, FoxO4)." (PMID 36142156, 2022).
ulcerative colitis (1 paper, 2025). An inflammatory bowel disease involving the mucosal surface of the large intestine and rectum. "Clinical evidence further supports this mechanism, showing that patients with ulcerative colitis (UC) in remission exhibit significantly higher levels of FoxO4 expression compared to those with active disease, with a positive correlation observed between FoxO4 expression and histological healing." (PMID 41394814, 2025).
vascular dementia (1 paper, 2024). A degenerative vascular disorder affecting the brain. "It protects against vascular dementia by reducing MDA levels, inhibiting ROS production, increasing glutathione peroxidase and total thiol levels, and up-regulating Nrf2, FOXO1, FOXO3, and FOXO4, thereby reducing oxidative stress and improving learning and memory functions." (PMID 39169952, 2024).
viral infections (1 paper, 2023). "However, its predicted target gene FOXO4 has shown aberrant expression in viral infections, such as HBV and EBV, in many investigations." (PMID 37577373, 2023).
tumor (78 papers, 2012 to 2025). "FOXO4 is known to be a tumour suppressor gene, the exon 2 mutation likely leads to loss of function due to the lack of FOXO functional domains." (PMID 38566894, 2024). "By analyzing differentially expressed genes which are associated with the generation of HNEs in AH group tumor, FOXO4 as a target has caught our attention." (PMID 39085238, 2024). "The loss of FOXO4 expression was associated with the degree of tumor differentiation and clinical stage based on the data from TCGA." (PMID 34055579, 2021). "FOXO4 expression was significantly decreased in GC, and loss of FOXO4 expression correlated with lymph node metastases and larger tumor size." (PMID 33463054, 2021). "Without producing asRNA, more FOXO4 mRNAs are retained in the T249A-CRISPR and increase of FOXO4 expression causes tumor suppression via cancer cell growth arrest." (PMID 32214089, 2020). "The presence of FOXO4-expressing cells in tumor tissue and their association with poor survival supports a role of FOXO4 in promoting stem cell properties resulting in poor outcomes." (PMID 27911272, 2017). "Single deletion of either Foxo1, Foxo3, or Foxo4 genes resulted in minor alterations in the incidence of neoplasms and lifespan; only triple knockout of Foxo1, Foxo3, and Foxo4 genes caused the cancer-prone phenotype and shortened lifespan." (PMID 25808402, 2015). "Deletion of all FOXO1, FOXO3, and FOXO4 alleles in adult mice induced a cancer prone phenotype, supporting a tumour suppressing function of these proteins." (PMID 22848740, 2012). "Reduced FOXO4 levels were associated with advanced N stage and large tumor size in GC." (PMID 33463054, 2021). "As FOXO4 expression is closely associated with tumor diameter and lymph node metastases, we speculate that loss of FOXO4 expression may enhance glycolysis activities in GC and provide the following evidence." (PMID 33463054, 2021). "Also, deletion of all FOXO1, FOXO3, and FOXO4 alleles in adult mice induced a cancer prone phenotype, supporting a tumour suppressing function of these proteins." (PMID 22848740, 2012). "The novelty of this study lies in the first demonstration that the natural product‐derived molecule FLLL31 induces tumor cell apoptosis by targeting the FOXO4/BCL6 axis." (PMID 41438489, 2025). "This activation of AKT by copper catalyzes the phosphorylation and subcellular redistribution of forkhead box O1a (FoxO1a) and forkhead box O4 (FoxO4), thereby fostering cancer cell proliferation and tumor growth." (PMID 38693584, 2024). "In the present study, we armed to the effects of 4-HNE on EVs formation, tumor cell growth, and migration, and we also found that FOXO4 activity positively correlated with 4-HNE levels." (PMID 39085238, 2024). "We performed RT-PCR analysis on FOXO4 genes and found that FOXO4 expression was significantly downregulated in tumor tissues which were inoculated with AH cells." (PMID 39085238, 2024). "The AKT activation triggered by copper can further catalyze the phosphorylation and subcellular redistribution of forkhead box O1a(FoxO1a) and forkhead box O4(FoxO4), which promoted the cancer cell proliferation and tumor growth." (PMID 36882769, 2023). "Previous study reported that FoxO1 and FoxO3 were two major participants involved in regulating tumor cell survival under Trastuzumab treatment, therefore, we evaluated the expression states of FoxO1, FoxO3, FoxO4 and FoxO6." (PMID 35835735, 2022). "The result showed that the deletion of FOXO1 and FOXO4 genes, and the increase in CNVs in the FOXO3 gene, were linked to tumor progression." (PMID 36555288, 2022).
tumor (continued). "Three cancer census genes, FOXO4 (NM_005938: p.S71C), GNAQ (NM_002072: p.T96S) and PDGFRB (NM_002609: p.V568E), acquire mutations as the tumor progresses to malignancy." (PMID 34816314, 2022). "In silico investigation showed that both the tumour repressors Forkhead box protein O4 (FOXO4) and PDCD4 are candidate targets of miRNA-499-5p and direct binding of miRNA499-5p to 3’-UTR of the mRNAs was confirmed using luciferase assays." (PMID 35847932, 2022). "Forkhead box O4 is a transcriptional factor involving multiple physiological functions and regarded as a tumor suppressor in many cancers." (PMID 34631691, 2021). "Concomitantly, the expression of FOXO4 is negatively correlated with the level of miR-150, and overexpression of FOXO4 significantly reduces tumor cell invasion in vitro." (PMID 34692488, 2021). "RdRP generates small interfering RNAs complementary to a tumor suppressor gene FOXO4, degrading mRNAs of FOXO4, reducing protein expression and consequently leading to tumor formation." (PMID 34350118, 2021). "In summary, these findings suggest that FOXO4-DRI can reduce the pSTAT3 activity of tumor cells and promote tumor cell apoptosis by targeting senescence-like CAFs in vivo." (PMID 34877934, 2021). "In HCC cells, the PI3K/AKT/FOXO4 signaling pathways are involved in cellular proliferation, tumor survival and other oncogenic processes." (PMID 33562611, 2021). "FOXO4 acts as a tumor suppressor in multiple human cancers, such as lung, leukemia, cervical, pancreatic and CRCs etc.." (PMID 34692488, 2021). "By the analysis of Bioinformation Databases, there was a significant interaction of FOXO4 down expression to clinical tumor stages and pathological grades in the patients with HNSCC." (PMID 34055579, 2021). "Forkhead box O 4 (FOXO4), a key albumen in the forkhead box O (FOXOs) family, plays crucial roles as a tumor suppressor in the cancer development." (PMID 34055579, 2021). "Expression levels of FOXO4 inversely correlate with tumor formation and incidence of clinical metastasis." (PMID 32214089, 2020). "The FoxO family, which consists of FoxO1, FoxO3, FoxO4, and FoxO6, is known as a tumor suppressor that limits cell proliferation and induces apoptosis." (PMID 32508033, 2020). "Taken together, these observations confirmed that increase of FOXO4 expression in T249A-CRISPR brings about a decrease of tumor formation in vivo." (PMID 32214089, 2020). "Nevertheless, it makes sense that two potential oncoproteins, such as CSN6 and COP1, are involved in degrading a tumor suppressor FOXO4 to promote cell proliferation, survival, and cancer growth." (PMID 33101846, 2020). "FOXO4 is a member of the Forkhead (Fox) transcription factor O family and was initially identified as a tumor suppressor which limits cell proliferation and induces apoptosis." (PMID 32228643, 2020). "Consistent with FOXO4 providing a role of tumor suppressor, T249A-CRISPR expressing higher levels of FOXO4 formed less and smaller tumors in mouse xenograft model." (PMID 32214089, 2020). "Further examination of these tumor model samples demonstrates that FOXO4 expression levels, and SGOC pathway genes are regulated according to the CSN6 knockdown." (PMID 33101846, 2020). "FOXO4 has a tumor suppressive role, but its further upstream regulators remain not well characterized." (PMID 33101846, 2020). "In summary, our study identifies CK1α as a critical mediator of 26 S proteasome-dependent turnover of FOXO3A and FOXO4 tumour suppressors in RAS-mutant cancer cells." (PMID 28945225, 2018).
tumor (continued). "The FOXO family members, FOXO1, FOXO3 and FOXO4, are ubiquitously expressed transcription factors that function as tumor suppressors through inhibiting the expression of genes promoting proliferation, survival or de-differentiation." (PMID 27966458, 2017). "For example, activation of FOXO4 reduces oncogene HER2-mediated tumor cell growth in vitro and in vivo through inhibiting AKT activity and maintaining p27Kip1 stability." (PMID 27976702, 2016). "Knockdown of endogenous FOXO4 expression is able to promote tumor cell metastasis and hinder metastasis inhibition effects caused by inhibition of miR-150, suggesting that FOXO4 is a key downstream metastatic effector of miR-150." (PMID 27976702, 2016). "In light of these important studies, it is likely that FOXO4 has a tumor suppressive function that is inactivated in tumorigenesis." (PMID 27027443, 2016). "The FOXO family of transcription factors (FOXO1, FOXO3A, and FOXO4) function as redundant tumor suppressors in lymphocytes." (PMID 25576920, 2015). "In the present study, we found the FOXO4 expression in non-tumorous tissues was consistently stronger than that of the GC samples, and GCs showed a lower expression level of FOXO4 in metastatic lesions compared to the corresponding primary tumor samples." (PMID 24886657, 2014). "Critically, FLLL31 exhibits enhanced bioavailability and metabolic stability relative to parental curcumin, enabling selective tumor cytotoxicity via coordinated upregulation of FOXO4, activation of BCL6, and suppression of Bcl‐xL‐mediated mitochondrial apoptotic inhibition." (PMID 41438489, 2025). "FOXO4 as a tumor suppressor induces apoptosis and prevents proliferation and invasion." (PMID 38589525, 2024). "In summary, these results suggest that AQP1 overexpression may enhance tumor progression by interacting with the transcriptional regulation networks governed by FOXO4, MAZ, and E2F TFs." (PMID 38057925, 2023). "Cytoplasmic FoxO3a and FoxO4 proteins were expressed in metastatic cells in the 4TLM group, similarly to FoxO1, and their expression levels were higher in the 4TLM compared to 67NR and tumor-free groups (p ˂ 0.05)." (PMID 36142156, 2022). "Although the involvement of FOXO4 has been investigated in tumor development as a downstream target of the PTEN/PI3K/AKT signaling pathway, few reports have discussed FOXO4 expression in HCC and its association with survival, prognosis, and drug resistance in patients with cancer." (PMID 34123834, 2021). "We then showed FOXO4 as a tumor suppressor through both in vitro and in vivo studies in GC." (PMID 33463054, 2021). "FOXO4, as a transcription inhibitor, one of its important functions is to inhibit tumor growth." (PMID 34692488, 2021). "Our results suggested that FOXO4 might play an important role in tumor deterioration and is a potential treatment target in CRC." (PMID 34631691, 2021). "Though miR-421 has been identified to target multiple mRNAs to alter tumor progression, such as FOXO4, MEF2D, and MTA1, whether miR-421 can target PDE7B remains to be uncovered." (PMID 33817314, 2021). "Furthermore, we explored the specific mechanisms by which FOXO4-DRI promotes tumor radiosensitivity." (PMID 34877934, 2021). "Increasing evidence has shown that dysregulation of FOXO4 expression could accelerate tumor progression including cervical, colorectal, pancreatic, and lung cancers." (PMID 34055579, 2021). "The mRNA level of FOXO4 was significantly related to tumor pathological grade." (PMID 34055579, 2021). "However, FOXO4 plays the role of tumor suppressor only by regulating the expression of downstream effector genes." (PMID 34631691, 2021).